BRCA2 (BRCA2 DNA repair associated)
Diseases named in the same sentence as BRCA2 in open-access papers (continued):
Sharing a sentence is not in itself a finding about the gene and the disease.
breast cancer (continued). "Moreover, stratified analyses by the cancer type and source of control observed significantly increased risk associated with BRCA2 N372H in subgroups with ovarian cancer, non-Hodgkin lymphoma and population-based controls, but not breast cancer or hospital-based controls." (PMID 25348552, 2014). "Among these 51 cancer genes the most prominent breast cancer genes BRCA1, BRCA2, and Chk2 were present." (PMID 24550935, 2014). "If the same tendency is true for defects in other high penetrance breast cancer genes, tumors from genetically related patients would exhibit related molecular subtypes, as it is the case for BRCA1 and BRCA2 families." (PMID 24479546, 2014). "In addition, there is little data on how systemic vitamin D status might interact with other known breast cancer risk factors including genetic (BRCA1, BRCA2, ATM), endocrine (estrogen, progesterone) and environmental (radiation, carcinogens) modulators of breast cancer development." (PMID 24982636, 2014). "Breast cancer tumor suppressors BRCA1, BRCA2 and PALB2 form a complex and play key roles in homologous recombination (HR), DNA double strand break (DSB) repair and cell cycle regulation following DNA damage." (PMID 23585894, 2013). "It has been shown in prostate cancer and in breast cancer that BRCA1 and BRCA2 are indeed co-regulated in response to DNA damage." (PMID 23613873, 2013). "About 5–10% of familial breast cancers can be attributed to two autosomal dominant genes with high penetrance: BRCA1 and BRCA2." (PMID 24171172, 2013). "The Ashkenazi Jewish population has been reported to have higher rates of breast cancer compared with other Caucasian populations, which may be at least partially explained by its high prevalence of two founder mutations in BRCA1 and one founder mutation in BRCA2." (PMID 23668689, 2013). "Given that the BRCA2-expression is correlated with poor prognosis in clinical cases, we investigated the outcome of abnormal DSS1 expression in human breast cancer cases." (PMID 24289229, 2013). "Here, we aim to analyze gene expression in breast cancer cell lines exposed to hypoxic condition with a focus on genes involved in DNA damage repair (DDR), especially BRCA2." (PMID 24171172, 2013). "The majority of BRCA1-related tumors are basal-like breast cancers characterized by ER, PR and HER2 negativity while BRCA2-tumors resemble sporadic cases." (PMID 22405187, 2012). "Four cases (6.6%) had multifocal disease with 2 cases of bilateral breast cancer, of which one was a metachronous BRCAX tumour with a 10 year interval and the other a BRCA2 carrier with contralateral tumour occurring 12 years after the primary lesion." (PMID 23146383, 2012). "We performed an immunohistochemical analysis of RAD21 expression in a cohort of 94 familial breast cancers (28 BRCA1, 27 BRCA2, and 39 BRCAX) and correlated these data with genotype and clinicopathologic parameters, including survival." (PMID 22537934, 2012). "BRCA2 mutation status did not appear to correlate with a distinct clinicopathological phenotype or disease behaviour, and a strong trend was seen within BRCA2 carrier tumours containing areas of micropapillary carcinoma possible suggesting a possible BRCA2 male breast cancer phenotype." (PMID 23146383, 2012).
breast cancer (continued). "These were likely laboratory contaminants, as the majority of them aligned to the breast cancer 1 and 2, early onset genes (BRCA1 and BRCA2), and targeted sequencing of these genes was conducted in the laboratory where the sequencing libraries were prepared." (PMID 22998755, 2012). "Compared with female breast cancers (logistic regression), promoter hypermethylation was less common in a variety of genes, particularly ESR1 (P = 0.005), BRCA1 (P = 0.010) and BRCA2 (P < 0.001)." (PMID 22765268, 2012). "PUBMED and AJOL database were searched for publications addressing Breast Cancer and BRCA1 and BRCA2 genes." (PMID 23519070, 2012). "First, of the women in whom breast cancer developed at 35 years or younger, 28.0% of women with TNBC were BRCA1 or BRCA2 carriers compared with only 9.9% among those who developed non-TNBC (P = 0.045)." (PMID 23116406, 2012). "PUBMED was searched using the following words in various combinations; ‘Breast Cancer’, ‘BRCA1’, ‘BRCA2’, ‘BRCA’, ‘Genes’, ‘Cancer Genes’, and ‘Africa’." (PMID 23519070, 2012). "After counseling of the index patient and obtaining informed consent, analysis of the breast cancer genes BRCA1 and BRCA2 and testing for HNPCC was performed." (PMID 23164213, 2012). "The KRAS-variant was found in 22.7% (n = 5/22) of patients with two separate primary breast cancers and ovarian cancer; 0% (0/12) of BRCA1 patients, 33.3% (1/3) of BRCA2 patients and 57.1% (4/7) of uninformative patients." (PMID 22662244, 2012). "Similar to our earlier findings in sporadic breast cancers, increased RAD21 expression in BRCA2 and BRCAX cancers confers a poor prognosis and resistance to DNA-damaging chemotherapeutic agents." (PMID 22537934, 2012). "Correlation of RAD21 expression with breast cancer-specific survival was further assessed for BRCA1, BRCA2, and BRCAX cancers." (PMID 22537934, 2012). "Methylation is involved in the development of female breast cancer, with frequent methylation of PAX6, BRCA2, PAX5, WT1, CDH13 and MSH6 in ductal carcinoma in situ and invasive ductal cancer." (PMID 22765268, 2012). "Two major high-penetrance breast cancer genes, BRCA1 and BRCA2, are responsible for approximately 20% of hereditary breast cancer (HBC) cases in Finland." (PMID 21356067, 2011). "We measured changes in telomere length in 19 mother-daughter pairs from FBOC families (3 BRCA1, 1 BRCA2, and 15 BRCAX) who developed breast cancer and compared them to 16 normal mother-daughter pairs." (PMID 21829373, 2011). "The occurrence of age anticipation in mother-daughter pairs with breast cancer was analyzed in 623 FBOC families, classified as BRCA1 (40 families), BRCA2 (52 families), and BRCAX (531 families)." (PMID 21829373, 2011). "In the current expanded cohort, we estimate the 10-year contralateral breast cancer risks to be 24% for BRCA1 carriers and 19% for BRCA2 carriers." (PMID 21487411, 2011). "In other breast cancer cell lines such as MCF-7 and MDA-MB-231, similar sensitivity to PARP inhibition was observed when BRCA2 was depleted." (PMID 21504625, 2011). "Lifetime risks of BRCA1/2 mutation carriers have been estimated at approximately 80% for breast cancer and approximately 40% and approximately 20% for ovarian cancer (BRCA1 and BRCA2, respectively)." (PMID 20920338, 2010). "Ratio of the forward (BRCA2) and the reverse (ZAR2) activity in the G0/G1 and S/G2 growth phases of different breast cancer cells using transient transfection with the dual reporter/promoter construct." (PMID 20202217, 2010).
breast cancer (continued). "We divided breast cancer into distinct disease end points and used data on the proportion of ER-negative and ER-positive tumours in BRCA1 and BRCA2 carriers and the general population to derive age-specific incidences of ER-negative and ER-positive disease." (PMID 20482762, 2010). "The median age of breast cancer onset ranges from 40-50 years in BRCA1 and BRCA2 carriers compared with 60-70 years in sporadic cases." (PMID 20961453, 2010). "For relatives of carriers, the female breast cancer SIRs were 13.13 (95% CI 6.57–26.26) and 12.52 (5.21–30.07) for BRCA1 and BRCA2, respectively." (PMID 20877337, 2010). "More recently, evidence has been presented from several studies to suggest that heterozygous carriers of BRCA1 and BRCA2 mutations, and breast cancer patients without such alterations may be distinguished based on mRNA profiling of fibroblasts and lymphoblastoid cell-lines (LCLs)." (PMID 20174566, 2010). "The role of breast cancer related genes, BRCA1 and BRCA2, in the NHEJ pathway suggests that the mechanisms involved in DNA DSB repair are of particularly important during breast tumorigenesis." (PMID 20808786, 2010). "Sixty breast cancer patients, derived from 60 families, were selected for molecular genetic testing of BRCA1 and BRCA2 genes." (PMID 20579331, 2010). "Two different human breast cancer cell lines (MCF-7, MDA-MB-231) and a human fibrocystic breast cell line (MCF-10a) were transfected by a pool of BRCA2-siRNA." (PMID 19442290, 2009). "In Ontario and British Columbia, women with a strong family history of breast cancer are eligible for genetic testing for BRCA1 and BRCA2." (PMID 19088722, 2009). "Our results suggest that variation in genes in IGF signaling also modify breast cancer penetrance in BRCA1 and BRCA2 carriers." (PMID 19843326, 2009). "However, the triple-negative phenotype is not characteristic of BRCA2-associated breast cancers." (PMID 19298662, 2009). "Finally, the absence of any BRCA1 or BRCA2 mutation in majority of "high-risk" families with breast-ovarian cancer support the general hypothesis that additional breast cancer susceptibility genes remain to be identified." (PMID 19619314, 2009). "Cox proportional hazards regression was used to model time from birth to diagnosis of breast cancer for BRCA1 and BRCA2 carriers separately." (PMID 19843326, 2009). "Immunoperoxidase staining for HIF-1α, PHD1, PHD2, PHD3, VEGF and FIH was carried out in 125 (38 BRCA1, 33 BRCA2 and 54 BRCAX) breast carcinomas." (PMID 19724277, 2009). "Currently, there is interest in identifying directed treatments for breast cancer in BRCA1 and BRCA2 carriers." (PMID 18577985, 2008). "We have now updated BOADICEA using additional family data from two UK population-based studies of breast cancer and family data from BRCA1 and BRCA2 carriers identified by 22 population-based studies of breast or ovarian cancer." (PMID 18349832, 2008). "We included in the study ten familial breast cancer samples, which carried sequence changes in BRCA1 or BRCA2, that are believed to be of little clinical significance." (PMID 18497862, 2008). "The ultimate aim of this experiment was to establish if gene expression profiles could distinguish between BRCA1 or BRCA2 pathogenic mutation carriers and familial breast cancer cases whose disease was not attributable to BRCA1 or BRCA2 mutations (BRCAX cases)." (PMID 18497862, 2008). "In choosing this, the overall male breast cancer incidences over the BRCA1, BRCA2 and polygenic effects were constrained to agree with the population incidences." (PMID 18349832, 2008).
breast cancer (continued). "The uncertainties surrounding the most appropriate treatment of breast cancer in BRCA1 and BRCA2 gene carriers is of critical importance and must be resolved in order that clinicians can better tailor treatment in hereditary breast cancer." (PMID 17697367, 2007). "Metcalf and colleagues have shown that RT actually protects against local recurrences and ipsilateral breast cancer among BRCA1 and BRCA2 carriers." (PMID 17428320, 2007). "Many of the known hereditary breast cancer genes such as BRCA1, BRCA2, CHEK2, ATM, and FANCJ/BRIP1 work together in a DNA repair pathway, raising the possibility that other genes in this pathway also predispose to breast cancer." (PMID 18053174, 2007). "Approximately 3% to 5% of breast cancer is estimated to be due to a dominantly inherited gene, and two breast cancer genes, BRCA1 and BRCA2, account for approximately 85% of families with four or more cases of breast and ovarian cancer." (PMID 18053174, 2007). "As for breast cancer cells, BRCA1 and BRCA2 levels were increased by ⩾2-fold at the lowest dose of I3C (20 μM)." (PMID 16434996, 2006). "For example several tumor suppressor genes known to play a role in breast cancer, such as RB1, PTEN and BRCA2, were frequently lost, but rarely gained, in our data set." (PMID 16457699, 2005). "Representative areas of all available breast cancer tissue specimens (n = 262) from 25 BRCA1, 20 BRCA2, and 74 non-BRCA1/2 breast cancer families were punched into a tissue microarray." (PMID 15987451, 2005). "Breast cancer tissue specimens (n = 262) from 25 BRCA1, 20 BRCA2 and 74 non-BRCA1/2 families were studied on a tumour tissue microarray." (PMID 15642173, 2005). "We identified a three-gene expression signature (BRCA2, DNMT3B and CCNE1) with independent prognostic significance in breast cancer (P = 0.007 by univariate analysis; P = 0.006 by multivariate analysis)." (PMID 15606925, 2004). "In a previous article, we described the development of a genetic model for familial breast cancer, which takes into account the simultaneous effects of BRCA1, BRCA2 and other genes." (PMID 15381934, 2004). "The ratio of ovarian to breast cancers was on average 0.41 : 1 for BRCA1 families and 0.07 : 1 for BRCA2 families (P=0.015)." (PMID 15026808, 2004). "The average number of breast cancer cases was comparable (3.70 in BRCA1 and 3.72 in BRCA2 families; P=0.965)." (PMID 15026808, 2004). "Fifth, our study did not include data on high‐impact breast cancer variants, such as those located in BRCA1 and BRCA2, which limits a comprehensive examination of their potential influence on breast cancer risk." (PMID 40944570, 2026). "All breast cancer patients in the universal testing group underwent BRCA1, BRCA2 and PALB2 testing." (PMID 41568010, 2025). "In the US, it is estimated that only 10% of those without a history of breast cancer who are BRCA1 or BRCA2 carriers have been identified and these unaffected women account for approximately 220,000 of the over 348,000 variant carriers." (PMID 40862808, 2025). "Moreover, HBOC increases the likelihood of multifocal and synchronous breast cancers; in a cohort of BRCA carriers, MF/MC disease occurred in 25% overall and was more than twice as frequent in BRCA2 than in BRCA1." (PMID 41209903, 2025).
breast cancer (continued). "Approximately 72% of BRCA1 carriers and 22–34% of BRCA2 and PALB2 carriers diagnosed with breast cancer present with triple-negative breast cancer (TNBC) a particularly aggressive biologic subtype that almost always necessitates chemotherapy even if tumors are small at diagnosis." (PMID 40275390, 2025). "HRD extends beyond BRCA1/BRCA2 mutations to include non-BRCA genes (RAD51C/RAD51D, BRIP1, BARD1, ATM, PALB2), broadening actionable targets across ovarian and breast cancer subtypes, including HER2-positive (30–40%) and luminal subtypes (15–25%)." (PMID 40864792, 2025). "As in breast cancer, ovarian cancer breakpoint distributions clustered around NPC breakpoints, even without a hereditary BRCA1 or BRCA2 gene mutation driver." (PMID 39885374, 2025). "We used data on 3,046 BRCA1 and 3,264 BRCA2 PV carriers, and 2,857 non-carrier female relatives of PV carriers from the Epidemiological Study of Familial Breast Cancer (EMBRACE)." (PMID 40399999, 2025). "This large cohort study of women with breast cancer who underwent germline testing provided information about BRCA1 and BRCA2 in a population enriched for Hispanic women and reported the prevalence of P/LP variants when universal BRCA1 and BRCA2 testing is offered to women with breast cancer." (PMID 40952741, 2025). "The peptides upregulate suppressors NR3C1, BRCA1, BRCA2, SFN, and RB1, which may initiate apoptosis processes and growth regulation in breast cancer cells, potentially preventing tumor progression." (PMID 40043049, 2025). "The most well-known genes are those related to breast cancer 1 and 2 (BRCA1 and BRCA2)." (PMID 40940924, 2025). "This study emphasizes CYP4B1, CYP4F12, and CYP4F3 gene expression levels, presenting tumor versus normal tissue analysis, their expression adjusted by stages, their correlation with BRCA1, BRCA2, and ESR1, the estrogen receptor status, and the overall survival analysis in breast cancer patients." (PMID 40723371, 2025). "The two breast cancer genes BRCA1 and BRCA2 are crucial in the DNA repair process." (PMID 39745016, 2025). "Although the sample size for the analysis was sufficient, GT for BRCA1 and BRCA2 was not conducted for all breast cancer cases at the time of the study." (PMID 40323562, 2025). "When β1 is large, β2>12β1, as is observed for BRCA1, BRCA2 and PALB2 for breast cancer." (PMID 39749474, 2025). "We compared the distributions of breast cancer risk factors including ANM, AAM, the interval between ANM and AAM, menstrual cycle length, height and BMI in a cohort of BRCA1 and BRCA2 PV carriers, and non-carriers, from a large national study." (PMID 40399999, 2025). "In male breast cancer, HRD prevalence is ~30%, driven by epigenetic silencing of BRCA2 and RAD51C." (PMID 40864792, 2025). "Consistent DFS, BCSS, and OS results as in the entire cohort were observed between BRCA1 and BRCA2 carriers with hormone receptor–positive and hormone receptor–negative breast cancers." (PMID 39993249, 2025). "Heritable breast cancer (BC) is influenced by well-known high-penetrance genes such as BRCA1, BRCA2, PALB2, and CHEK2, but the contribution of many moderate- and low-penetrance genes remains unclear." (PMID 41463216, 2025). "In BRCA2 carriers, there were no deaths from breast cancer in those undergoing RRM versus 0.9% in those electing for surveillance, precluding the calculation of hazard ratios." (PMID 38248108, 2024). "Even though many are not yet diagnosed with breast cancer, approximately 46% of BRCA1 mutation carriers and 52% of BRCA2 mutation carriers are diagnosed with breast cancer at some point in their lifetime." (PMID 38791944, 2024).